RET (ret proto-oncogene)
Diseases named in the same sentence as RET in open-access papers (continued):
Sharing a sentence is not in itself a finding about the gene and the disease.
lung cancer (continued). "RET testing may also guide the choice of cytotoxic therapy, given that RET-driven lung carcinomas demonstrate increased sensitivity to a pemetrexed-based treatment." (PMID 37445709, 2023). "Mutations in lung cancer driver genes (KRAS, EGFR, BRAF, ALK, ROS1, MET, RET, and ERBB2) in the high- and low-risk groups were shown on a waterfall plot, which demonstrated that the low-risk group (20%) harbored a higher EGFR mutation frequency than did the high-risk group (8%)." (PMID 36353226, 2022). "Among the detected alternations, the eight-major driver mutations of lung cancer (EGFR, ALK, ERBB2, MET, RET, ROS1, BRAF, and KRAS) could be found in 14 out of 17 (82.4%) patients using both surgical and CNB specimens." (PMID 36224661, 2022). "In particular, RET fusion lung cancer has been reported to show a slower clinical course." (PMID 36452495, 2022). "Because RET fusions occur in lung cancer, RET-targeted therapy has been attempted by clinicians." (PMID 35223529, 2022). "RET gene rearrangements are identified in 1–2% of lung cancer patients." (PMID 35329956, 2022). "Likewise, a study involving 7858 lung cancer patients which compared mutations between patients aged ≤45 vs >45 years observed a higher prevalence of ALK, ROS1 and RET fusions, ERBB2 exon-20 insertions and EGFR exon-19 deletions in younger patients." (PMID 36263208, 2022). "Limit of detection of RET fusion detection by lung cancer compact panel is no more than 1% variant allele frequency." (PMID 36452495, 2022). "Known lung cancer-associated fusions, including BRAF and RET, were also identified." (PMID 36675685, 2022). "Summary of clinical trials of RET inhibitors for RET fusion-positive lung cancer." (PMID 34497761, 2021). "Summary of clinical data of RET inhibitors for RET fusion-positive lung cancer." (PMID 34497761, 2021). "Previous studies also showed that RET fusion-positive lung cancer patients may benefit a lot from pemetrexed-based treatments; therefore, treatment regimens that include immunotherapy and chemotherapy must be considered." (PMID 34497761, 2021). "Recent discoveries of ROS‐1 and RET rearrangement have led to the development of novel targeted agents, and BRAF, MET, and NTRK mutations have also emerged as targets in the treatment of lung cancer." (PMID 33960703, 2021). "Rearrangements in RET are found in 1%-2% of all NSCLC; moreover, RET point mutations are not frequently found in lung cancer but play a key role in hereditary neuroendocrine syndromes such as MEN2B." (PMID 35004309, 2021). "For RET fusion-positive lung cancer patients, this is good news." (PMID 34497761, 2021). "Current guidelines consequently note that single gene testing for the presence of RET fusions is not recommended on a stand-alone basis in patients with advanced NSCLC, but suggest that RET analysis should form part of any large multigene panel test developed for patients with lung cancer." (PMID 33553195, 2020). "RET-rearranged lung cancers can be heterogeneous in terms of concomitant genetic alterations." (PMID 32295619, 2020). "Notably, we identify MYC as a protein that is upregulated by RET expression and downregulated by treatment with cabozantinib, opening up potentially new therapeutic avenues for the combinatorial targetin of RET fusion- driven lung cancers." (PMID 33318047, 2020). "The findings remind us that the RET fusion gene is likely to play an important role in the occurrence of brain metastasis in lung cancer patients, and it is expected that further basic research will be conducted to elucidate the mechanisms underlying this clinical phenomenon." (PMID 31769228, 2020). "The next‐generation sequencing (NGS) method was used to detect eight genes (EGFR, ALK, KRAS, ROS‐1, BRAF, ERBB2, RET, and c‐MET) and statistical analysis was used to determine which genes were the driving factors for brain metastasis associated with lung cancer." (PMID 31769228, 2020).
lung cancer (continued). "We retrospectively included 129 patients with RET-rearranged lung cancer from 13 centers." (PMID 32295619, 2020). "Selective inhibition of RET has shown more promise in lung cancer." (PMID 33318047, 2020). "RET is fused with genes such as KIF5B or CCDC6 in approximately 1% of lung cancers." (PMID 30943926, 2019). "Inhibition of p38, similarly to RET inhibition, decreased the highly migratory phenotype of lamin B1–depleted lung epithelial cells and lung cancer cells, supporting the notion that activation of the RET/p38 signaling axis mediates the increased migratory and invasive phenotype upon lamin B1 loss." (PMID 31015297, 2019). "To analyze whether there is a correlation between lamin B1 and RET levels in lung cancer patients, we analyzed RET expression in a human lung tissue microarray." (PMID 31015297, 2019). "Seventy-four patients with RET-rearranged lung cancers were identified." (PMID 31192313, 2019). "Fusions involving the oncogenic gene RET have been observed in thyroid and lung cancers." (PMID 30446652, 2018). "Furthermore, the inhibition of the EGF signaling by EGFR small interfering RNA (siRNA), anti-EGFR antibody (cetuximab), and EGFR-TKi (Iressa) determined an increase in the sensitivity to RET inhibitors in lung cancer cells carrying CCDC6-RET fusion." (PMID 29455670, 2018). "Mechanisms of acquired resistance to RET tyrosine kinase inhibitors in lung cancers are largely unknown." (PMID 29434222, 2018). "Excitingly, early reports from a clinical trial in lung cancer suggests that this combination may also improve delivery of RET inhibitor across the blood-brain barrier, essential for treating brain metastases." (PMID 30666215, 2018). "Fusions of the gene RET have been described in thyroid and lung cancers." (PMID 30446652, 2018). "Although RET rearrangements are infrequent, screening as part of a multigene panel or in patients where other lung cancer genes have been excluded, is recommended to identify patients who may benefit from RET targeted therapies (below)." (PMID 30666215, 2018). "Also the prevalence of the RET fusions greatly increases (from a median 1.8% to a significative 6.3%) when evaluated in 159 lung cancer patients wild type for EGFR, ALK, ROS1, BRAF, KRAS, HER2." (PMID 29455670, 2018). "We also speculate on the role of CCDC6 as common partner of at least two TK, ROS1 and RET, for its targeting in combined therapies including TKIs in lung cancer treatment." (PMID 29455670, 2018). "In addition to the ALK rearrangements, other fusion transcripts of the genes for ROS proto-oncogene 1 (ROS1), ret-proto-oncogene (RET) or NTRK genes have been identified in 1–2% of patients with advanced stage lung cancer." (PMID 28805673, 2017). "KIAA1217 is a novel RET partner gene in lung cancer and contains two CCDs that could promote ligand-independent dimerization in the RET fusion protein." (PMID 27150058, 2016). "We analyzed 214 mutations across 26 lung cancer-associated genes and three fusion genes using the MassARRAY® LungCarta Panel and the ALK, ROS1, and RET fusion assays in 198 consecutively resected lung adenocarcinomas from never-smoker females at a single institution." (PMID 25760072, 2015). "For example, Achaete-Scute homologue-1 (ASCL1), a pro-neural transcription factor, is important in pulmonary neuroendocrine cell development, injury repair, and highly expressed in neuroendocrine differentiated lung cancer functioning as a regulator of RET oncogene." (PMID 25705890, 2015). "For example, in a study using a split FISH assay to evaluate 1528 lung cancers, 22 tumors were detected with split RET signals, of which 12 were confirmed as fusions with KIF5B and one with CCDC6 and the remaining nine tumors showed little or no expression of the RET kinase domain." (PMID 25881079, 2015).
lung cancer (continued). "With the development of molecular subtype in lung cancer, NSCLC patients with EGFR-WT had been identified to carry several new “driver mutations”, including KRAS, HER2, and BRAF mutations, as well as ALK, ROS1, and RET gene fusion." (PMID 25277203, 2014). "Since RET rearrangements have also been found in lung cancer, this mechanism may be of broad significance and involved in generation of chromosomal rearrangements in other regions of the genome and in multiple cancer types." (PMID 24040417, 2013). "This method facilitates the molecular evaluation for RET fusions and could be applicable in clinical practice to detect lung cancer that may be responsive to RET inhibitors." (PMID 23342255, 2012). "Normal signals are frequently seen in lung cancer cells that also display RET gene rearrangements." (PMID 23342255, 2012). "In a previous study conducted by the University of California Lung Cancer Consortium, 54.9% of patients had EGFR mutations, 32.9% of patients had KRAS mutations, 5.3% of patients had ALK fusions, and < 3% of patients had other mutations (HER2, MET, RET, ROS1, or BRAF-non-V600E)." (PMID 39009968, 2024). "Similarly sparse are reports concerning lung cancer and RET fusions and FDG PET." (PMID 39272672, 2024). "Molecular testing with a targeted panel of 8 lung cancer-associated driver genes detected a novel PIBF1-RET (P16:R12) fusion, which putatively encodes a gene in which the first 16 exons of PIBF1 was concatenated to RET exon 13 and its downstream sequence, retaining the RET kinase domain." (PMID 37478265, 2023). "Indeed, an analysis by Wang and colleagues determined that RET fusion-positive lung carcinomas had more poorly differentiated tumors compared to those with ALK or EGFR alterations, indicating that RET fusions define a unique molecular and clinicopathological subtype of NSCLC." (PMID 35957881, 2022). "Thus, definitive methods for detecting RET fusion-positive lung cancer need to be established." (PMID 34497761, 2021). "MET mutations in lung cancer are considered to be predictors of susceptibility to the MET inhibitor crizotinib, whereas RET translocations are correlated with a positive response to targeted therapy with RET inhibitors such as cabozatinib, vandetinib, and alectinib." (PMID 33198090, 2020). "Since our findings revealed decreased expression of lamin B1 in the majority of lung carcinoma patients, targeting of RET, or p38 signaling, might be a valuable therapeutic strategy for a significant fraction of human lung tumors caused by perturbation of the lamin B1–EZH2 axis." (PMID 31015297, 2019). "As a corollary, the same general diagnostic approach using a suite of novel SMART kits could also be equally applied to target and detect clinically significant RET and ROS1 fusions that are associated with the disease progression of other types of lung cancers." (PMID 27409166, 2016). "RET fusion gene with an identifiable clinical pathological features, is present in some subsets of lung cancer, and its treatment is effective by RET inhibitor, suggesting that RET fusion gene may be a new target for individualized treatment to the subgroup of NSCLC." (PMID 24229630, 2013). "Moreover, immunoprecipitation analysis revealed that each of these RTKs formed a heterodimer with MET, demonstrating for the first time that EGFR, HER2, HER3, and RET are the main heterodimerisation partners of MET in MET amplification-positive lung cancer cells." (PMID 21847121, 2011). "The discovery of therapeutically targetable gene fusions, such as ALK, RET, ROS1, and NTRK1, has significantly advanced lung cancer management." (PMID 39810398, 2025). "The most frequent cancer types were lung cancer (108, 67.5%), including 62 NSCLC with RET fusion-positive, colorectal cancer (14, 8.8%), and breast cancer (11, 6.9%)." (PMID 40016191, 2025).
lung cancer (continued). "Specifically, in the field of lung cancer, this catalog advocates the inclusion of PD-L1, EGFR, ALK, ROS-1, KRAS, NTKR, RET, and MET." (PMID 40261489, 2025). "The principal RET fusion partners in non–small-cell lung cancer (NSCLC) are kinesin family member 5B (KIF5B) (70–90%) and CCDC6 (10–25%), followed by NCOA4-RET, TRIM33-RET, ZNF477P-RET, ERCC1-RET, HTR4-RET, CLIP1-RET fusions (18%)." (PMID 41465145, 2025). "In patients with lung cancer, ALK was detected in 14% (17/118), CMET was detected in 61% (78/128), HER2 was detected in 73% (16/22), and RET was detected in 4% (4/90)." (PMID 40075672, 2025). "EML4-ALK fusions, RET rearrangements, ROS1 fusions, and NTRK1/2/3 fusions are observed at a cumulative frequency of 3 %–10 % in lung cancers." (PMID 40503459, 2025). "Discovery and drug development of new lung cancer‐related targets: EGFR, ALK, ROS1, RET, MET, BRAF inhibitors, etc." (PMID 40135802, 2025). "Most patients with lung cancers harboring NTRK gene fusions exhibit clinical characteristics similar to those with ALK, RET, or ROS1 fusions, and are often found in a younger population with minimal or no smoking history." (PMID 39199653, 2024). "The remarkable clinical responses observed in RET fusion-positive lung cancer, RET-mutant MTC, and other RET-driven malignancies highlight the potential of these inhibitors to significantly improve outcomes for patients facing these challenging cancers." (PMID 39272672, 2024). "This panel, which was specifically designed for the detection of 63 known lung cancer-specific fusion genes, including ALK, RET, and ROS1 fusion genes, successfully identified SLC45A-ROS1 fusions in two patient samples." (PMID 38472960, 2024). "We looked at the distribution of breakpoints in ALK, RET, ROS1, NTRK1, as well as other kinase genes known to generate oncogenic fusions in lung cancer, such as EGFR, ERBB4, MET, FGFR3, and EPHA245." (PMID 38877018, 2024). "In 2012, RET fusions were initially detected in non-small cell lung cancer (NSCLC), which are present in 1%–2% of lung cancer patients." (PMID 39372862, 2024). "Lung cancer present the highest diversity of driver types in both cohorts and ALK (36%, 10/28) and RET (28%, 4/14) sole reciprocal fusions were the top driver genes in our and MSK cohort, respectively." (PMID 39254060, 2024). "Similar to the FHD patients with RET fusion-positive a/mNSCLC, the most common treatments were chemotherapy (27.3%, n = 6/22) for the CDM lung cancer patients who received prior anti-cancer treatment." (PMID 39594790, 2024). "Non‐small cell lung cancers with ERBB2 amplification, MET activation, KRAS G12C, RET, and ROS1 fusion resulted in the second‐highest frequency of recommendations." (PMID 36251535, 2023). "The benefit of immunotherapy appears limited in most oncogene-addicted lung cancer subtypes, including ALK and ROS1 and potentially RET- and HER2-altered lung cancer." (PMID 38132389, 2023). "Retroviral transduction of SETD2ΔN in both mouse KrasG12DSetd2–/– lung cancer cells and JHRCC12 kidney cancer cells downregulated RET, supporting a regulation of RET by SETD2 in both lung and kidney cancers." (PMID 36810256, 2023). "A high sensitivity next generation sequencing (NGS) panel system: lung cancer compact panel, with RNA assay using cytological brushing solution, confirmed the fusion gene KIF5B exon 15; RET exon 12 (K15RET12)." (PMID 36452495, 2022). "Based on our integrated cohort and the TCGA LUAD cohort, we identified 28774 high-confidence alternative splicing events (ASEs), which affected 8726 genes, including targets for tyrosine kinase inhibitors used to treat lung cancer, such as EGFR, RET, and MET." (PMID 35989380, 2022). "Genetic testing for advanced nonsmall cell lung cancer (NSCLC) includes EGFR, ALK, ROS1, BRAF, MET, HER-2, RET, NTRK1/2/3, PI3K, and PD-L1." (PMID 35368895, 2022).
lung cancer (continued). "Selpercatinib also abrogates tumor growth of lung cancer and MTC xenografts in a dose-dependent manner in vivo, highlighting its therapeutic utility in RET-dependent cancers." (PMID 35957881, 2022). "The rearranged during transfection proto-oncogene (RET) and v-ros proto-oncogene (ROS1) have also been identified as fusion types that contribute to lung cancer by leading to constitutive activation of kinase." (PMID 36081848, 2022). "Sequentially, we evaluated the targetable variations detected ability in different samples, including EGFR, ALK, BRAF V600E, KRAS, MET ex14 skipping, RET, ROS1, ERBB2, which have high evidence in lung cancer." (PMID 36167530, 2022). "We found eight genes relevant to lung cancer (PDGFRB, RET, KRAS, KEAP1, ROS1, STK11, MET and ALK), for which integrating clinical data with our TME features clearly improves the ability to predict mutations in these genes." (PMID 36131239, 2022). "In line with previous reports, our analysis recapitulated the key targetable oncogenic fusion events in lung cancers, with a 4.2% frequency of ALK fusions, 1.3% of RET fusions, and 1.2% of ROS1 fusions." (PMID 36369474, 2022). "Lung cancer patients harboring therapeutically actionable fusion genes, such as ALK, RET, and ROS1, have experienced clinical benefits owing to the development of effective targeted therapies with crizotinib being foremost." (PMID 36081848, 2022). "A previous study in 36,813 Chinese lung cancer patients, focusing on eight key lung cancer driver genes (EGFR, ALK, MET, KRAS, ERBB2, ROS1, RET, and BRAF), revealed a prevalence of 0.03% for P/LP germline mutations." (PMID 35428225, 2022). "Multiple oncogene fusions are currently targeted in lung cancer treatment, such as those involving ALK, RET, NTRK and ROS1 among many others." (PMID 34680187, 2021). "One such panel is the Ion Ampliseq RNA fusion lung cancer panel offered by ThermoFisher Scientific, Waltham, USA, which targets 70 known fusion transcripts of ALK, RET, ROS1, and NTRK." (PMID 34571741, 2021). "For lung cancer, we collect the status of the National Comprehensive Cancer Network (NCCN) recommended biomarkers: EGFR, ALK, BRAF, ROS1, KRAS, RET, NTRK and PD-L1." (PMID 33572220, 2021). "Especially in lung cancer, various targeted therapies have been developed, ranging from EGFR-TKIs and BRAF, ALK, ROS, RET, MET, TRK1, and HER2 inhibitors, to more recent developments in KRAS inhibitors." (PMID 34359729, 2021). "We assessed the expression of IFNAR1 in MDSC from transplantable models of B16 melanoma, LLC lung carcinoma, CT26 colon carcinoma, and genetically engineered models of melanoma (RET) and pancreatic cancer (KPC)." (PMID 33741967, 2021). "Here, we performed a retrospective analysis to determine the imaging features and metastatic patterns of advanced RET+ NSCLC, specifically as compared to those of ALK+ and ROS1+ NSCLC, the most common oncogenic fusions in lung cancer." (PMID 32183422, 2020). "In this frame, it has been shown that the physical interaction between CCDC6-RET and the EGFR facilitates signaling and reduces efficacy of RET kinase inhibition in a lung cancer cell line." (PMID 32326537, 2020). "Multi-kinase RET inhibitors, such as cabozantinib and RXDX-105, are active in lung cancer patients with RET fusions; however, the overall response rates to these two drugs are unsatisfactory compared to other targeted therapy paradigms." (PMID 33318047, 2020). "A previous study showed that targetable activating alterations in lung cancer genes, such as EGFR, ALK, RET and ROS1, are mutually exclusive molecular events." (PMID 32729257, 2020). "In conclusion, selective RET inhibition with LOXO-292 achieved a clinically meaningful and confirmed response in a patient with a RET fusion-positive lung cancer with leptomeningeal disease and heavily pretreated brain metastases." (PMID 31485557, 2019).